NKG7 (natural killer cell granule protein 7)
Diseases named in the same sentence as NKG7 in open-access papers (continued):
Sharing a sentence is not in itself a finding about the gene and the disease.
tumor (continued). "The cell type-specific markers we used for cell annotation were as follows: T cell (CD3D); NK cell (KLRD1 and NKG7); plasma cell (IGKC and JCHAIN); Mast cell (KIT and TPSB2); tumour cell (CA9, NDUFA4L2 and SLC17A3); endothelium (PECAM1, PTPRB and KDR); mesangial cell (ACTA2 and PDGFRB)." (PMID 40830065, 2025). "Additional research from the same group showed that NKG7 was upregulated on intertumoral antigen-specific CD8 + T cells and NK cells and was essential for the infiltration and accumulation of T cells within the tumor microenvironment." (PMID 41194247, 2025). "Similarly, FGFBP2+ NK cells also highly expressed markers like GNLY, NKG7, and PRF1, indicating a strong anti-tumor immune response." (PMID 39093451, 2024). "We show that tumor cells have an increased expression of several markers (CD47, IL7R, NKG7, CD80, CD84, CSF1R, NLRC5/CITA, CD2 and IRF3) that may be involved in regulating the level of immune infiltration and the effect on tumor immunity." (PMID 39001353, 2024). "Notably, NK cells, which displayed high expression levels of GNLY, NKG7, CCL3, and KLRD1, were enriched in tumor tissues, especially in HM tissues." (PMID 37612267, 2023). "We also noted that the tumor enriched C5 cells were characterized by the expression of resting NK cells markers, such as AREG, XCL1, and KLRC1, while the C9 cells, which expressed the CX3CR1 and NKG7, were abundant in normal tissues." (PMID 36008393, 2022). "Given our observation that Nkg7-/- CD8+ T cells form a prolonged and inefficient synapse, we next investigated the consequence of this on the transcriptional response of the T cells upon recognition of a tumor target." (PMID 35874669, 2022). "However, decreased NKG7 expression alters the number, transport and calcium release of cytosolic particles, leading to reduced CD8+ T cell-mediated tumour cell killing." (PMID 35473583, 2022). "Together these data demonstrate that hypersecretion of TNF in the absence of NKG7 compensates for inefficient synapse-mediated cytotoxicity to control MC38-OVA tumor growth." (PMID 35874669, 2022). "The increased expression of cytotoxic effector molecules GZMA, GZMB, GZMH, GZMM, GNLY, NKG7, and PRF178 but also of the thioredoxin function inhibitor TXNIP79, demonstrates a potent effector capacity to eliminate malignant cells and suppress tumor growth." (PMID 33602930, 2021). "Although CD8_Exh cells still express some cytotoxic-related genes like GZMB and NKG7, their overall function is in a hyporesponsive state and may not effectively kill tumor cells." (PMID 41394809, 2025). "We identified several spatial biomarkers linked to non-recurrence, including elevated NKG7 expression in CD45+ immune cell regions (p = 0.0011) and higher TFPI2 and PIGR expression in tumor areas (p = 2.09 × 10−6), both associated with improved progression-free survival." (PMID 40422184, 2025). "Notably, as long as tumor cells were kept in excess (at least 2 tumor cells per T cell), the relative rate of killing of Nkg7-/- T cells was reduced to same level regardless of changes in the number of targets in the culture." (PMID 35874669, 2022). "To test this, we challenged cohorts of C57BL/6J Nkg7+/+ and Nkg7-/- littermate mice with the mouse colon carcinoma tumor line, MC38-OVA; a model in which the growth of tumors is acutely controlled by endogenous OVA-reactive CD8+ T cells in the 3 weeks following tumor inoculation." (PMID 35874669, 2022). "These genes were defined as the tumor reactive signature (TRS), including co-inhibitory receptors (CTLA4, PDCD1, TIGIT and HAVCR2), reactive markers (CD38 and ENTPD1), effector molecules (NKG7 and PRF1), tumor necrosis factor TNFRSF9 and critical exhaustion-related regulator TOX." (PMID 34804045, 2021). "Our analysis uncovered a role for NKG7 in enhancing the efficiency, but not capacity, of CD8+ T cells to form immune synapses with tumor targets and trigger cell death." (PMID 35874669, 2022).
tumor (continued). "Indeed, in the absence of NKG7, CD8+ T cells remained capable of killing tumor targets, but at a markedly slower rate." (PMID 35874669, 2022). "Consistent with our findings in Nkg7+/+ and Nkg7-/- littermates, Nkg7 sgRNA-electroporated OT-I T cells (sgNkg7) demonstrated significantly reduced killing of MC38-OVA tumor cells compared to OT-I T cells electroporated with a non-targeting control guide (sgNT)." (PMID 35874669, 2022). "To test this hypothesis in vivo, we challenged cohorts of C57BL/6J Nkg7+/+ and Nkg7-/- littermate mice with MC38-OVA-Tnfrsf1a-/- tumors and monitored tumor growth, with or without depletion of CD8+ T cells." (PMID 35874669, 2022).
cancer (48 papers, 2019 to 2025). A tumor composed of atypical neoplastic, often pleomorphic cells that invade other tissues. "Some markers CD14 (monocyte), CD3D (CD4+T cells), CD3E (CD8+T cells), CD68 (macrophage), CST3 (myeloid cells), GNLY (NK cells), KRT18 (epithelial cells), and NKG7 (NK cells) were positively associated with TMSB10 in all cancers." (PMID 37275863, 2023). "NKG7 in CD8+ T cells is also elevated in some cancer patients with durable response to immunotherapy." (PMID 40837024, 2025). "NKG7 expression in CD8+ T cells was also elevated in some cancer patients who showed durable response to immunotherapy." (PMID 40837024, 2025). "Cancer patients with low NKG7 expression tend to be poor responders to immunotherapy, whereas immunotherapy responders often exhibit expansions of NKG7-expressing T cells." (PMID 39989459, 2025). "NKG7 is critical for controlling cancer initiation, growth, and metastasis and regulating lymphocyte granule exocytosis and downstream inflammation." (PMID 37615858, 2024). "As we known, the NKG7 gene was critical for controlling cancer initiation, growth, and metastasis upregulated in the responder, Similarly, upregulated in NK cells and CD4 T cells at the single cell resolution." (PMID 37152010, 2023). "CD8+ cytotoxic T cells had elevated expression of the cytotoxic markers PD-1, Gzmb, Gzmk, Prf1, Nkg7, Eomes, Irf8, Klrd1, Fyn, Nfatc1, Tnfrsf9, and Zap70, supporting their killing function against cancer cells." (PMID 37762216, 2023). "NKG7 expressed by natural killer cells was critical for controlling cancer initiation, growth and metastasis." (PMID 35741779, 2022). "The cancer cell subtypes enriched in the cancer region were CRABP2 + cancer cells (Epi-C3), and NK cells (T/NK-C5: NKG7) and mast cells (Mye-C0: TPSB2, Mye-C9: CPA3) were also located in the cancer region." (PMID 36434043, 2022). "NKG7 is expressed in natural killer cells and T cells, and closely involved in host-defense mechanisms against infection and cancer, as well as the immune response regulation." (PMID 34393665, 2021). "Natural killer cell granule protein 7 (NKG7) is a marker of NK cells that is critical for controlling cancer initiation, growth, and metastasis." (PMID 34504794, 2021). "Notably, NKG7 expression on NK cells has been demonstrated to be crucial in controlling cancer initiation, growth, and metastasis." (PMID 41194247, 2025). "This could have implications for cancer patients on immune checkpoint inhibitors, as low NKG7 expression in CD8+ T-cells has been shown to predict poor responders to anti PD-1 therapy." (PMID 37077913, 2023). "The most important reason we think is that, compared with GZMH, NKG7 is closer to CD8+ T cells, as a number of reports have indicated that NKG7 is required for CD8+ T immune activity in antitumor cytotoxicity, cancer immunotherapy, and anti‐inflammation." (PMID 40761479, 2025). "In specific, TIS is referred to as an 18‐gene signature (CCL5, GZMK, CD3D, CD3E, CD2, HLA‐DRA, IL2RG, NKG7, CIITA, CXCR6, LAG3, TAGAP, HLA‐E, CXCL13, IDO1, CXCL10, STAT1, and GZMB), which was related to the response to ICIs in various cancers." (PMID 37434432, 2023). "At present, the relationship of RIPK2 with GZMB, NKG7 and PRF1 in cancer is still unclear, and this still needs to be explored in the occurrence, development, treatment and prognosis of cancer." (PMID 35473583, 2022). "Further analysis revealed a significant decrease in antitumor factors (GZMA, GZMB, NKG7, and PRF1) in CD8T cells and an increase in the proportion of cancer cells, especially in the cancer-cell-dominant group." (PMID 36497182, 2022). "The hypergeometric distribution showed that in the cancer region, TM4SF1 + cancer cells (Epi-C0) colocalized with the two subtypes of NK cells (T/NK-C4: GNLY and T/NK-C5: NKG7) and mast cells (Mye-C0: TPSB2, Mye-C9: CPA3)." (PMID 36434043, 2022).
cancer (continued). "Despite the relatively small size of the patient cohort, a trend of better overall survival was observed in AML patients with cancer tissues that had lower expression of IFNGR2 and higher expression of NKG7." (PMID 31921143, 2019). "Additionally, NK EVs have been shown to reproduce key functions of their parent NK cells and to contain Natural Killer Cell Granule Protein 7 (NKG7), a gene critical for controlling cancer initiation, growth, and metastasis." (PMID 38256278, 2024). "Our findings revealed a positive correlation between the expression levels of LAG3 and IFNG (R = 0.76, p < 0.001), PRF1 (R = 0.75, p < 0.001), FASLG (R = 0.75, p < 0.001), GZMH (R = 0.74, p < 0.001), NKG7 (R = 0.74, p < 0.001), and PDCD1 (R = 0.73, P < 0 0.001) in pan-cancer tissues." (PMID 38115039, 2023). "NKG7 is the only gene that positively related to both ADA1 and ADA2 in three cancers." (PMID 35663977, 2022). "Similarly, NKG7, ARHGAP9, C1QA, and CD53 were accurately predicted in 15/28 datasets (R = 0.38–0.46 for the various cancer types)." (PMID 32747659, 2020). "In addition to transcription factors, in AML samples, we identified the upregulation of genes that were reported to accelerate leukaemogenesis, including S100A8, S100A9, and RPS26, and the downregulation of genes related to cancer control and defence, such as XIST, GIMAP7, NKG7, and GNLY." (PMID 37615858, 2024). "At present, the role of NKG7 in cancer has not been elucidated." (PMID 34531849, 2021). "For example, in COAD case, NKG7 and TBC1D10C are included in the Up target list, but neither of these have been cited in the immune/cancer literature, nor in curated annotation resources such GeneRef, GeneOntology, and IHOP, to the best of our knowledge." (PMID 31227749, 2019).
infection (15 papers, 2020 to 2025). The state of being infected such as from the introduction of a foreign agent such as serum, vaccine, antigenic substance or organism. "Compared to “transient” CD8 T cells, the “durable” CD8 T cells upregulated the expression of chemokines such as CCL4 and CCL5, which attract immune cells to the site of infection, as well as cytotoxic protein marker NKG7." (PMID 38561339, 2024). "We noted that many genes were upregulated and preserved after infection, including Nkg7, Ccl5, Ifng, and Ccl4, which reinforces that MAIT cells had acquired an altered cellular state." (PMID 34272362, 2021). "Calculating the differentially expressed genes revealed that genes such as Nkg7, Lgals1, Pdcd1, and Ccr2 were significantly upregulated in expanded cells in at least one infection condition and demonstrated consistent trends in expression for all infection groups." (PMID 35185882, 2022). "Comparisons across the early- and late-stages of infection showed that cells from CHs had an early expression of genes associated with exhaustion (PDCD1, ENTPD1), and cytotoxicity, including NK-like genes NKG7, GNLY, KLRC2, and KLRC3 (encoding for NKG2C and NKG2E, respectively)." (PMID 36477661, 2022). "Furthermore, several additional transcripts associated with innate effector cell function were upregulated throughout acute infection, compared to pre-infection, including NKG7, KLRD1, EOMES, CD160, SLAMF5, and IL12RB1." (PMID 31937782, 2020).
NKG7 also shares sentences with these, for which no sentence is quoted: cutaneous melanoma (3 papers); colitis (2); lung adeno-carcinoma (2); B-cell CLL (1); bacterial sepsis (1); breast invasive carcinoma (1); celiac disease (1); Cirrhosis (1); colon adenocarcinoma (1); coronary heart disease (1); dengue (1); eosinophilia (1); glioma (1); hepatocellular carcinoma (1); HIV-1 infection (1); hypersensitive pneumonitis (1); hypertensive (1); lung carcinoma (1); malaria (1); mesothelioma (1); metastatic disease (1); ovarian carcinoma (1); polyp (1); rectum adenocarcinoma (1); rheumatoid arthritis (1); scleroderma (1); skin tumor (1); thyroid carcinoma (1); type 1 diabetes mellitus (1); uveal melanoma (1).
A further 1 disease shares a sentence with NKG7 in 1 paper.